SCN4A (sodium voltage-gated channel alpha subunit 4)
Description:
Pore-forming subunit of Nav1.4, a voltage-gated sodium (Nav) channel that directly mediates the depolarizing phase of action potentials in excitable membranes. Navs, also called VGSCs (voltage-gated sodium channels) or VDSCs (voltage-dependent sodium channels), operate by switching between closed and open conformations depending on the voltage difference across the membrane. In the open conformation they allow Na(+) ions to selectively pass through the pore, along their electrochemical gradient. The influx of Na+ ions provokes membrane depolarization, initiating the propagation of electrical signals throughout cells and tissues. Highly expressed in skeletal muscles, Nav1.4 generates the action potential crucial for muscle contraction.
Synonyms: Nav1.4; HYPP; SkM1; CMS16; CMYO22A; CMYP22A; HOKPP2; HYKPP; NAC1A; Na(V)1.4
Tractability: Small molecule: an approved drug acts on it; a structure with a bound ligand is known; a high-quality ligand is known; it belongs to a druggable protein family. Antibody: UniProt places it where antibodies can reach, with high confidence; its Gene Ontology location is reachable by antibodies, with high confidence; UniProt predicts a signal peptide or a membrane-spanning region. PROTAC: a small molecule that binds it is known.
Target class: Voltage-gated ion channel; Voltage-gated sodium channel; Ion channel
Gene: Protein-coding gene on chromosome 17 (63,938,554 to 63,972,918, reverse strand). Ensembl gene ENSG00000007314.
Subcellular location: Cell membrane
Subcellular location (Human Protein Atlas): Golgi apparatus
Pathways (Reactome):
Developmental Biology: Interaction between L1 and Ankyrins
Muscle contraction: Phase 0 - rapid depolarisation
Gene Ontology:
Molecular function: protein binding; voltage-gated sodium channel activity; monoatomic cation channel activity; monoatomic ion channel activity
Biological process: regulation of skeletal muscle contraction by action potential; sodium ion transmembrane transport; cardiac muscle cell action potential involved in contraction; muscle contraction; sodium ion transport; action potential; monoatomic ion transport; transmembrane transport
Cellular component: plasma membrane; voltage-gated sodium channel complex; membrane
Genetic constraint (gnomAD): Loss-of-function variants: 80 observed, 153.39 expected, observed/expected ratio (o/e) 0.52, 90% interval 0.43 to 0.63. The upper end of that interval is the gene's LOEUF score, 0.63, which puts it in group 2 of 6, group 1 being the genes least tolerant of losing a copy. Missense variants: 2,150 observed, 2,453.7 expected, observed/expected ratio (o/e) 0.88, 90% interval 0.85 to 0.91. Synonymous variants: 929 observed, 984.56 expected, observed/expected ratio (o/e) 0.94, 90% interval 0.89 to 1.
Gene-disease validity (ClinGen):
ClinGen rates the evidence that SCN4A causes each of these diseases.
SCN4A-related myopathy, autosomal recessive (autosomal recessive): Definitive. Any congenital myopathy in which the cause of the disease is a mutation in the SCN4A gene.
Homologues: Orthologues: chimpanzee SCN4A (99% identical), macaque SCN4A (98% identical), dog SCN4A (94% identical), pig SCN4A (93% identical), guinea pig SCN4A (93% identical), rat Scn4a (93% identical), mouse Scn4a (93% identical), rabbit SCN4A (93% identical), tropical clawed frog scn5a (68% identical). Paralogues in human: SCN2A (70% identical), SCN3A (69% identical), SCN1A (69% identical), SCN8A (68% identical), SCN9A (67% identical), SCN5A (66% identical), SCN10A (58% identical), SCN11A (48% identical), SCN7A (46% identical), CACNA1A (25% identical), CACNA1D (25% identical), CACNA1S (25% identical), and 14 more.
Diseases named in the same sentence as SCN4A in open-access papers:
SCN4A is named in the same sentence as 108 diseases in open-access papers, as found by Europe PMC text mining. Sharing a sentence is not in itself a finding about the gene and the disease. The quoted sentences say what the papers report.
Myotonia (68 papers, 2009 to 2025). An involuntary and painless delay in the relaxation of skeletal muscle following contraction or electrical stimulation. "SCN4A gain-of-function mutation encoding NaV1.4 channels can disable channel inactivation so that INaP in skeletal muscles elicits repetitive AP firing in some forms of myotonia or induces electrical silence in periodic paralysis." (PMID 41465576, 2025). "Mutations in the SCN4A have been linked to various neuromuscular disorders in humans, including myotonia (G1306E), hyperkalemic periodic paralysis (T704M), and myasthenic myopathy (R1454W)." (PMID 39932879, 2025). "SCN4A mutations have been shown to be associated with myotonia, paramyotonia congenita, and periodic paralyses." (PMID 38187266, 2023). "Mutations in SCN4A can lead to Hyper-, Hypo- or Normo-kalemic Periodic Paralysis or to different forms of myotonia (Paramyotonia Congenita-PMC and Sodium Channel Myotonia-SCM and severe neonatal episodic laryngospasm-SNEL)." (PMID 36081873, 2022). "Co-existing mutations in CLCN1 and SCN4A seem to enhance the myotonia and/or muscle pain in DM2 patients." (PMID 35205411, 2022). "Other symptoms include muscle hypertrophy, more frequent in Becker’s disease and conferring a “hercules” habitus to the patient, and cold sensitivity of myotonia, although less frequent than in patients carrying SCN4A mutations." (PMID 34208776, 2021). "Since all SCN4A mutations linked to myotonia induce a gain-of-function of Nav1.4, carriers of the R1463H mutation should be diagnosed with sodium channelopathy, PC or SCM." (PMID 33670307, 2021). "This study demonstrates that CLCN1-p.W322* and SCN4A-p.R1463H mutations can act alone or in combination as inducers of myotonia." (PMID 33670307, 2021). "A first clinical example of a C-terminal Nav1.4, SCN4A, mutation associated with human disease is cold-aggravated myotonia, which causes transient myotonic stiffness or renders fibres transiently inexcitable resulting in a periodic paralysis." (PMID 34643236, 2021). "Overall, SCN4A mutations resulting in defects of slow inactivation and delay of time to peak in resurgent Na+ currents are likely factors contributing to constant myotonia and weakness in SCM patients." (PMID 32276507, 2020). "Although eyelid myotonia has been previously identified as a hallmark of SCN4A-related myotonia, we were unable to characterize its prevalence in this cohort, as it was not commonly commented on in the charts reviewed." (PMID 32670189, 2020). "We report a patient with a de novo heterozygous SCN4A variant c.2386C>G; p.L796V who had congenital anomalies and early-onset myotonia." (PMID 32117035, 2020). "Autosomal dominant SCN4A mutations were first linked to hyperkalemic periodic paralysis, then subsequently included paramyotonia congenita, several variants of myotonia, and finally hypokalemic periodic paralysis." (PMID 32117035, 2020). "All SCN4A myotonia mutations studied produce a gain-of-function effect of Nav1.4, resulting in defects of channel inactivation or enhancement of activation, which explain the dominant inheritance pattern of the diseases." (PMID 32010054, 2019). "The WES data confirm the infant does carry a paternally inherited known pathogenic SCN4A mutation, shown previously to be functionally deleterious, with neurophysiological evidence of myotonia in the father." (PMID 31440732, 2019). "In summary, we report a pathogenic SCN4A mutation, previously associated with myotonia, in a child with epilepsy and concurrent apneas." (PMID 31440732, 2019). "For example, Scn4a gene codes for the alpha subunit of the voltage-dependent sodium channel, and mutations in this gene have been associated with sodium channel myotonia." (PMID 30906902, 2018). "Similar gain-of-function alterations in channel function are the hallmark of SCN4A variants in patients with myotonia, including in infants with severe respiratory complications." (PMID 29605429, 2018).
Myotonia (continued). "Other SCN4A mutations described in patients affected by myotonia caused an increased window current, and this was proposed as causative mechanism for the tissue hyperexcitability." (PMID 30038349, 2018). "Mutations in SCN4A gene typically produce several different subtypes of skeletal muscle disorders consisting mainly of clinical and electrophysiologic myotonia or periodic paralyses." (PMID 28330959, 2017). "Here, we found one homozygous missense mutation G1306A (Glycine to Alanine) in SCN4A gene in one patient with mild painful myotonia." (PMID 26885337, 2015). "Here we report a novel pathological mutation in the SCN4A gene in a patient presenting with myotonia and periodic paralysis." (PMID 25348630, 2014). "Here we report the discovery of a novel SCN4A mutation (c.1762A>G; p.I588V) in a patient with myotonia and periodic paralysis, located within the S1 segment of the second domain of the Nav1.4 channel." (PMID 25348630, 2014). "In-depth characterization of draggen mice, a novel mouse model of myotonia and periodic paralysis, found alterations in whole animal metabolism caused by Scn4a mutations accompanied by inappropriate AMPK activation in mice." (PMID 25348630, 2014). "Here we report the identification of a novel dominant SCN4A mutation identified in a patient presenting with myotonia and periodic paralysis." (PMID 25348630, 2014). "The majority of dominant SCN4A causative mutations in periodic paralysis with myotonia have been found in the pore forming segments S5–S6 or the voltage sensor segment S4 of Nav1.4." (PMID 25348630, 2014). "For example, myotonia in the human disorder paramyotonia congenita caused by mutation in the SCN4A gene (OMIM: #168300) is aggravated and/or induced by exposure to cold temperatures (OMIM)." (PMID 19737145, 2009). "Low [Mg2+]o may exacerbate myotonia in patients carrying SCN4A mutation, but supplementation with magnesium helps reduce weakness and myotonia." (PMID 41465576, 2025). "SCN4A is the causative gene of hyperPP as well, and it is also responsible for SCN4A-related non-dystrophic myotonia, characterized by a heterogeneous phenotypic spectrum of myotonia." (PMID 36779057, 2023). "Mutations in Nav1.4 have been associated with various neuromuscular disorders, including SCN4A-related myotonia, paramyotonia congenita of von Eulenburg, congenital myasthenic syndrome, hypokalemic periodic paralysis type 2, hyperkalemic periodic paralysis and normokalemic periodic paralysis." (PMID 36614292, 2023). "The SCN4A associated myotonia commonly involves the facial muscles with eyelid myotonia; the muscle weakness can occur more frequently and may persist longer than in CLCN1 patients." (PMID 33263785, 2021). "More than 150 CLCN1 and at least 100 SCN4A myotonia-associated gene variants are currently known." (PMID 33263785, 2021). "Mutations affecting one SCN4A allele are often associated with a gain-of-function resulting in muscle stiffness (myotonia) that may worsen with repeated contraction (paramyotonia) as well as episodes of hyperkalemic periodic paralysis." (PMID 32117035, 2020). "Electromyographic evidence of myotonia in early infancy, as we observed at 6 weeks, is unusual and differentiates the weakness in our patient from the syndrome of congenital myopathy with hypotonia associated with recessive loss-of-function mutations of SCN4A." (PMID 32117035, 2020). "We characterized two novel mutations of the SCN4A gene expanding the knowledge about genetics of mild forms of myotonia, and we present, to our knowledge, the first homozygous patient with sodium channel myotonia." (PMID 32411069, 2020). "SCN4A gene mutations cause a number of neuromuscular phenotypes including myotonia." (PMID 31440732, 2019).
Myotonia (continued). "SCN4A/Nav1.4 is predominantly expressed in skeletal muscles, and mutations in Nav1.4 are associated with multiple skeletal muscle disorders including myotonia, paramyotonia congenita (PC), hyper or hypokalemic periodic paralysis (hyperPP or hypoPP), and congenital myasthenic syndrome (CMS)." (PMID 31357904, 2019). "K+ sensitivity of Na+ channel myotonia due to dominant SCN4A mutations is well known." (PMID 30420713, 2018). "The gain-of-function change we observed in the infant with Arg1463Ser is consistent with previously reported SCN4A variants (appendix pp 1–4) that, after a period of apparent clinical normality, cause myotonia of the laryngeal and respiratory muscles precipitating an abrupt onset apnoeic crisis." (PMID 29605429, 2018). "Yet we cannot exclude that the DM1 and SCN4A mutations may compound to increase the severity of her myotonia, as recently suggested." (PMID 27164696, 2016). "A novel SCN4A mutation was identified in a patient presenting with myotonia and periodic paralysis." (PMID 25348630, 2014). "Notably, myotonia in neonatal SCN4A may be associated to warm-up phenomenon or paradoxical, depending on the causing mutations, mainly the p.G1306E and p.I693T, respectively." (PMID 32849172, 2020). "The clinical phenotypes associated with this SCN4A mutation included sodium channel myotonia (SCM) (case 1), paramyotonia congenita (cases 2, 3, 4, 5, 7 and 8), and cold-aggravated myotonia (case 6) (case 6)." (PMID 40843127, 2025). "SCN4A is most commonly associated with dominant GOF variants, which are a well-established cause of various sodium channelopathies such as myotonia and hyperkalemic periodic paralysis." (PMID 38255008, 2024). "NDMs are mainly related to the reduced activity of the CLC-1 channels or impaired inactivation of the NaV1.4 channels caused by CLCN1 or SCN4A variants, which lead to sarcolemmal hyperexcitability manifesting as myotonia." (PMID 35350395, 2022). "In conclusion, NDMs are a group of hereditary skeletal muscle ion channelopathies characterized by myotonia and caused by CLCN1 or SCN4A variants, mainly including MC and PMC." (PMID 35350395, 2022). "Mutations in distinct myotonia-associated genes (CLCN1, SCN4A, DMPK, CNBP) can co-occur in a patient and modify the presentation compared to a patient carrying a single gene mutation." (PMID 34529042, 2022). "SCN4A myotonias are clinically classified into three subgroups: sodium channel myotonia (SCM), paramyotonia congenita (PMC), and hyperkalemic periodic paralysis (Hyper PP)." (PMID 34996390, 2022). "NDMs are a group of hereditary skeletal muscle ion channelopathies characterized by myotonia and caused by CLCN1 or SCN4A variants, including MC, PMC, and SCM." (PMID 35350395, 2022). "SCN4A-myotonias include paramyotonia congenita Eulenburg (PMC), potassium aggravated myotonia (PAM), and hyperkalemic periodic paralysis with myotonia (hyperPP)." (PMID 33263785, 2021). "We enrolled 70 patients (64 families): 48 (68.5%) patients had a diagnosis of CLCN1-myotonia and 22 (31.4%) of SCN4A-myotonia." (PMID 33263785, 2021). "In the current German guidelines on NDM, the measurement of CK is a mandatory part of the diagnostic testing and is stated to be no more than 5 × upper normal limits (UNL) for NDM-CLCN1 and often more than twice the UNL for SCN4A-myotonias." (PMID 33263785, 2021). "Patients presenting at birth with episodic laryngospasm or congenital myopathy-like phenotype with later onset of myotonia were considered as neonatal SCN4A." (PMID 32849172, 2020). "Discussion: Among the features reviewed, we did not identify clinical or electrophysiological differences to distinguish CLCN1- and SCN4A-related myotonia." (PMID 32670189, 2020). "Although painful myotonia is an accepted clinical feature of SCN4A-related myotonia, CLCN1-related myotonia was originally described as being painless." (PMID 32670189, 2020).
Myotonia (continued). "The genetic analysis showed the presence of 310–390 CTG repeats and a new SCN4A mutation in exon 19 (c.3473C>T, p.Pro1158Leu), indicating the coexistence of DM1 and sodium channel myotonia." (PMID 27164696, 2016). "Paramyotonia congenita, caused by SCN4A gene mutations, features myotonia triggered by cold and exercise, without potassium level changes." (PMID 41018978, 2025). "CLCN1 or SCN4A mutations lead to the dysfunction of the CLC-1 or NaV1.4 channel, which may predispose the muscle to sarcolemmal hyperexcitability manifesting as myotonia." (PMID 35350395, 2022). "The SCN4A gene encodes for the voltage-gated sodium channel NaV1.4, and its mutations are usually related to non-dystrophic myotonia, periodic paralysis, and myasthenic syndrome." (PMID 34722688, 2021). "Significant clinical overlap exists between CLCN1 and SCN4A myotonias." (PMID 33263785, 2021). "For example, a patient affected by non-dystrophic myotonia with a mutation in the SCN4A gene resulted positive to BrS with both flecainide and ajmaline challenges." (PMID 34722688, 2021). "In some patients with SCN4A-myotonia, we observed CK elevation up to 1100 U/L." (PMID 33263785, 2021). "Finally, our data suggest that it must be stressed that genetic testing in myotonia patients should include both CLCN1 and SCN4A genes, even if a mutation has been found in one of them." (PMID 33670307, 2021). "The pathophysiological mechanism of myotonia is mainly related to reduced activity of the chloride channels and consequently reduced chloride conductivity in CLCN1, whereas in SCN4A-myotonias it is caused by an impaired inactivation of the NaV1.4 channels." (PMID 33263785, 2021). "Myopathic features may be a component of the dominantly inherited SCN4A myotonic syndromes (sodium-channel myotonia, myotonia permanens, severe neonatal episodic laryngospasm, SNEL) or the late permanent muscle weakness of periodic paralysis." (PMID 32117035, 2020). "Out of the patients trialing at least one medication, none with SCN4A variants had discontinued all medication use for myotonia." (PMID 32670189, 2020). "Mutations in the genes encoding voltage-gated Cl− and Na+ channels (respectively, CLCN1 and SCN4A) produce a wide spectrum of phenotypes, which differ in age of onset, affected muscles, severity of myotonia, degree of hypertrophy, and muscle weakness, disease progression, among others." (PMID 32010054, 2019). "Thus, it should be considered as first line therapy for patients with concomitant SCN4A and CLCN1 mutations associated with myotonia." (PMID 31772215, 2019). "In our study, we investigated a DM2 patient with severe and early onset myotonia without mutations in CLCN1 or SCN4A genes." (PMID 30038349, 2018). "However, an association between DM2 patients with prominent myotonia and mutations on CLCN1 or SCN4A, encoding for the α subunit of the skeletal muscle sodium channel Nav1.4, have been found." (PMID 30038349, 2018). "Our larger cohort of 30 patients carrying the c.3466G>A p.A1156T mutation in the SCN4A gene showed a consistent phenotype of predominant myalgia, muscle stiffness, and exercise cramps without signs of clinical myotonia, paramyotonia, or periodic paralyses." (PMID 28330959, 2017). "Our mutational analysis confirms the role of single nucleotide polymorphisms in SCN4A gene in Iranian patients with non-dystrophic myotonias." (PMID 26885337, 2015). "Non-dystrophic myotonia results from mutations in the voltage-gated sodium channel encoded by the gene SCN4A." (PMID 24866741, 2014). "Mutations in the skeletal muscle channel (SCN4A), encoding the Nav1.4 voltage-gated sodium channel, are causative of a variety of muscle channelopathies, including non-dystrophic myotonias and periodic paralysis." (PMID 25348630, 2014).